VWF (von Willebrand factor)
Diseases named in the same sentence as VWF in open-access papers (continued):
Sharing a sentence is not in itself a finding about the gene and the disease.
tuberculosis (1 paper, 2017). A chronic, recurrent infection caused by the bacterium Mycobacterium tuberculosis. "ADAMTS-13 concentrations were lower in patients with HIV-tuberculosis who died than in survivors, possibly owing to higher concentrations of vWF." (PMID 28363198, 2017). "Concentrations of vWF and VCAM-1 were higher in mycobacteremic patients than in patients with HIV-tuberculosis without mycobacteremia, whereas concentrations of ADAMTS-13, Ang-1, and Tie-1 were lower." (PMID 28363198, 2017).
ulcerative colitis (1 paper, 2025). An inflammatory bowel disease involving the mucosal surface of the large intestine and rectum. "In conclusion, we identified a close association between COL1A1, LOXL2, VWF, MZB1, and ERS in the pathogenesis of ulcerative colitis (UC)." (PMID 40607383, 2025). "Through this approach, we demonstrated that COL1A1, LOXL2, and VWF may participate in the fibrotic pathological process of ulcerative colitis by regulating fibrosis-related pathways." (PMID 40607383, 2025).
uterine fibroid (1 paper, 2022). "We have highlighted the differential expression of 3 genes (BDNF, CCND1, and VWF) in our results that we think could play key roles in uterine fibroid etiology or pathogenesis." (PMID 36066972, 2022).
vascular anomaly (1 paper, 2022). Vascular anomalies are abnormalities or disorders of the vascular system, either in veins or arteries. "In patients with vascular anomaly entities other than KHE, vWF:Ag and vWF:CB were within normal ranges in most patients." (PMID 36551267, 2022).
Vasovagal syncope (1 paper, 2017). A vasovagal episode or vasovagal syncope is the most common form of reflex syncope. "Diagnosis vasovagal syncope was associated with less increase in VWF:Ag during HUT compared to other diagnoses (0.01 ± 0.16 vs. 0.09 ± 0.17; p = 0.004)." (PMID 28649180, 2017).
tumor (379 papers, 1995 to 2026). "VWF levels impact risk of not only cancer-related thrombosis but also tumor cell apoptosis, angiogenesis, and metastasis." (PMID 41536292, 2026). "VWF mutations cause functional deficits, often resulting in blood disorders and rare tumor formation." (PMID 40740229, 2025). "How do flow-induced platelet binding and VWF self-association between VWF secreted from EC, platelets, and tumor-derived VWF contribute to cancer adhesion and migration?" (PMID 39282473, 2024). "For example, the S1506L mutation in the gene for von Willebrand factor (VWF) occurs with a median VAF of 7.23% in TCGA-LUAD tumor samples containing the mutation, and in 4.90% of matched blood samples." (PMID 39172974, 2024). "According to the literature, neoplasia can cause adsorption of VWF to malignant cell clones or other cell surfaces and induce specific or non-specific autoantibodies that lead to increased degradation of VWF." (PMID 37762844, 2023). "Given the emerging findings suggestive of the broad role VWF plays in mediating tumor metastasis, it is tempting to consider the possibility of targeting the VWF and its associated interactions in anti-neoplastic therapy." (PMID 35327035, 2022). "There is also evidence from multiple tumor cell lines revealing their ability to direct endothelial activation and cause secretion of VWF from endothelial WPB." (PMID 35327035, 2022). "This potentially indicates that the primary tumour and the associated microenvironment drive the progressive increase of VWF in the plasma, which also correlate with cancer progression with time." (PMID 33571850, 2021). "EC-associated vWf staining was highly variable in both healthy ovarian tissue and tumor samples, preventing a quantitative evaluation of its expression." (PMID 29233846, 2018). "In contrast, analyses of tumor cell metastasis in VWF deficient mice clearly demonstrated that VWF deficiency significantly enhanced tumor metastasis, thus presenting VWF as an anti-metastatic protein." (PMID 28035064, 2017). "Knocking-down of Foxp3 expression blocks in vivo tumor growth in mice and prolongs mice's survival, which is associated with von Willebrand factor expression." (PMID 27557492, 2016). "Together, the data suggest that inhibition of Xa-mediated thrombin generation by the pentasaccharide Fondaparinux is not sufficient to block tumor-associated EC activation and luminal VWF fiber formation in the microenvironment of the tumor." (PMID 27602496, 2016). "Using a vWF-deficient mouse model, it was demonstrated that vWF plays a protective role against tumor cell dissemination in vivo by inducing apoptosis of metastatic cells, presumably early after their arrest in the microvasculature of the target organ." (PMID 26306290, 2015). "The association between AVWS and tumors has been reported, with VWF being absorbed by tumor cells." (PMID 40277845, 2025). "Besides these established roles of VWF in hemostasis and thrombosis, high VWF levels in cancer patients have been linked to tumor metastasis." (PMID 39282473, 2024). "We postulate that the dramatically shortened half‐life of VWF in this patient may have been caused by VWF antibody‐mediated inhibition and/or VWF adsorption onto platelets sequestered in the spleen or onto the massive number of tumor cells." (PMID 36051021, 2022). "Endothelial cell surface marker genes, CD31 (PECAM1) and von Willebrand factor (VWF), were also significantly elevated in high score tumors (both p < 0.001) indicating that high score is associated with increased concentration of blood vessels inside a tumor." (PMID 32933189, 2020). "It is evident that a deficiency of vWF causes a number of diseases; however, increased plasma levels of other cargo stored in WPBs are reported in cardiovascular and neoplastic diseases, and in the aging population they contribute to an increased risk of thrombosis." (PMID 31092558, 2019).
tumor (continued). "The cell types and markers we explored were as follows: tumor epithelial cells (E-cadherin as a marker), cancer-associated fibroblasts (CAFs; Collagen1A1), endothelial cells (Von Willebrand Factor [VWF]), the immune compartment (CD45), T cells (CD3G), myeloid cells (CD33), and macrophages (CD14)." (PMID 31765370, 2019). "The increase in CD34+ and VWF+ cells in DTs and RTs caused by the infiltration of circulating cells might increase vessel diameter, which is crucial for tumor recurrence after radiation." (PMID 31803626, 2019). "CD31, CD34, FKI-1, and von Willebrand factor are the most commonly used markers; however, mutation and poor differentiation of tumor cells may cause misdiagnosis, so comprehensive consideration of all these diagnostic approaches is important." (PMID 31804339, 2019). "To investigate whether the inhibition of vWF-GPIbα interaction was associated with tumor metastasis, we first investigated the effect of antibodies on the interaction between platelets and hypoxic-treated LCC cells in vitro." (PMID 30223883, 2018). "Nevertheless, contradictory findings were reported that vWF deficiency could promote tumor metastasis instead." (PMID 30223883, 2018). "vWF has been previously linked with tumor angiogenesis and progression." (PMID 29299165, 2017). "Furthermore, VWF was shown to directly induce apoptosis of tumour cells in vitro and caused death of metastatic cells arrested in the lungs." (PMID 25846632, 2015). "Furthermore, VWF was shown to directly induce apoptosis of tumor cells in vitro and caused death of metastatic cells arrested in the lungs." (PMID 21470136, 2011). "Given the rarity, it is hard to estimate the true prevalence of individual neoplasms based on registry data, though the most commonly reported cases are in association with Wilms tumors, which are thought to secrete a plasma factor that increases VWF clearance." (PMID 35327035, 2022). "CD34 is a well-known marker of angiogenesis and endothelial progenitor cells, whilst VWF is a multimeric plasma glycoprotein that mediates platelet adhesion to both the subendothelial matrix and endothelial surfaces and is associated with tumor survival and angiogenesis." (PMID 31803626, 2019). "Tumor cells are another cell type that might be susceptible to VWF-induced apoptosis." (PMID 23936617, 2013). "D-dimer and vWF have been associated with clinical outcomes in several cancer types and coagulation factors are known to play a key role in the generation of tumor stroma formation and in the expression and processing of VEGF and many other angiogenesis factors, including TSP, PlGF, and SDF-1." (PMID 23930208, 2013). "Anti-vWF stains large vessels more strongly than small ones and consequently our findings could reflect the immaturity of newly formed tumour-associated vessels." (PMID 11953822, 2002). "For example, blocking VWF in murine models of colonic carcinoma or melanoma impeded platelet-tumor interactions and development of metastatic disease." (PMID 41536292, 2026). "Inhibition of von Willebrand Factor (vWF); suppression of calcineurin activity; tumor microvessel density modulation; decrease in VEGF/VEGFR2 signaling and NFAT activation." (PMID 41155601, 2025). "VWF can promote pro-inflammatory signaling, regulate angiogenesis and vascular permeability, and thus promote tumor cell growth and vascular metastasis." (PMID 40740229, 2025). "Second, evidence suggests that in certain cancer patients, VWF is released not only from typical sources, such as endothelial cells and megakaryocytes, but also from tumor cells and the surrounding tumor microenvironment." (PMID 40699668, 2025). "Four primary cell populations were first identified using canonical cell markers: WT tumor cells (WT1, NCAM1, SIX1, SIX2, PAX2), cancer-associated fibroblasts (CAFs) (ACTA2, TAGLN, COL1A1, PDGFRB), endothelial cells (PECAM1, CLDN5, ENG, VWF) and immune cells." (PMID 40098972, 2025).
tumor (continued). "VWF is both a characteristic gene of endothelial cells and an upstream gene of hypoxia metabolism, playing a crucial role in tumor growth, metastasis, and angiogenesis." (PMID 39901877, 2025). "The TECs0 cluster was characterized by TPT1 and VWF expression and was involved in endothelial cell differentiation and angiogenesis regulation, promoting tumor expansion by ensuring an oxygen and nutrient supply." (PMID 40123905, 2025). "Endothelium-secreted VWF polymers contribute to tumor cell adhesion and transendothelial migration, which is critical for tumor transmission." (PMID 40740229, 2025). "We established a 7-plex mIF panel to detect lymphoid aggregates and TLS using markers against T cells (CD3), B cells (CD20), mature dendritic cells (Lamp3), macrophages (CD163), as well as endothelial cells (vWF) and tumor cells (pan-cytokeratin or MelA)." (PMID 40319321, 2025). "Downregulated were the critical genes CAV1, VWF, and DCN, suggesting loss of tumour-suppressive functions, and upregulated were SCGB2A1, CLDN4, and immune-related genes CCL3 and GZMB, promoting tumour growth and immune evasion." (PMID 41312167, 2025). "Canonical markers were used to annotate different cell types: malignant cells (COL1A1, IBSP), myeloid cells (CD74, CD14), osteoclasts (CTSK, MMP9), pericytes (RGS5, ACTA2), endothelial cells (PECAM1, VWF), and tumor-infiltrating lymphocytes (CD3D, NKG7)." (PMID 40730548, 2025). "For instance, the A3 CBD domain of von Willebrand factor (VWF) was fused with IL-2 to facilitate targeted cytokine delivery to tumors, capitalizing on the leaky vasculature typical of tumor tissues." (PMID 40557148, 2025). "Hypoxia metabolism and (Tumor mutation burden) TMB have a modest correlation, while VWF and EPAS1 are negatively correlated with TMB significantly." (PMID 39901877, 2025). "Immunohistochemistry for von Willebrand Factor (vWF) was performed to assess vasculature in normal rat lung tissue in comparison to the rat lung tissue with metastasised OS tumours." (PMID 41315643, 2025). "The results showed that in cells overexpressing hsa-miR-1972 with inhibited VWF expression, the expression of tumor malignancy indicators was significantly suppressed." (PMID 39529627, 2024). "In contrast to the data presented, a significantly increased risk of tumor progression and a poorer response during ICI therapy in metastatic patients with higher levels of vWF ag was observed in another prospective study." (PMID 39487855, 2024). "Another promising thrombogenic marker for the recognition of tumor progression is the von Willebrand factor (VWF)." (PMID 38893201, 2024). "Tumour cells can induce platelet activation via the secretion of major factors involved in the coagulation cascade including thrombin, von Willebrand factor, tissue factor and ADP3." (PMID 38233507, 2024). "CD34, CD31, and vWF are commonly used vascular marker proteins, and immunohistochemical (IHC) staining of these proteins can detect vascular formation in tumor tissues." (PMID 39230586, 2024). "Secretions from cancer cells (tumor-derived supernatant) can activate EC to secrete VWF, forming long strings attached on the EC surface, which can promote platelet and cancer cell adhesion with each other and on the EC surface." (PMID 39282473, 2024). "Studies have shown that vWF is an independent predictor of HCC occurrence and is associated with tumor mass, tumor growth, worsening of PHT, and metastatic dissemination acting on the STAT-3 pathway." (PMID 38611066, 2024). "The genes FLT1, VEGFC, VWF, and VEGFD are closely linked to angiogenesis and vascular function, playing important roles in tumor angiogenesis." (PMID 38486263, 2024). "vWF is considered a promotor of inflammation and an important mediator of tumor cell/platelet aggregation and metastasis among others by increasing vascular permeability and facilitating adherence and endothelial transmigration of CTCs." (PMID 39114075, 2024).
tumor (continued). "Compared to these uncertainties, the role of VWF in assisting tumor cell adhesion on EC is well established by many studies." (PMID 39282473, 2024). "Alternatively, fibrinogen, fibronectin, vWF, or single tumor cells immobilized on coverslips were used." (PMID 38764040, 2024). "Elevated vWF levels are known to contribute to cancer progression, as vWF can enhance platelet adhesion and aggregation, creating a pro-thrombotic environment that favours tumour metastasis." (PMID 39768338, 2024). "Von Willebrand factor (VWF) has been shown to play an important role in tumor cell adhesion to and extravasation from the endothelial cell lining of blood vessel walls during cancer metastasis." (PMID 39282473, 2024). "VWF multimers arrange platelet adhesion in vessels and probably participate in both vessel occlusion and tumor progression." (PMID 38893201, 2024). "VWF is stored within the Weibel–Palade bodies in ECs, whose activation determines its release in tumor microenvironment and blood circulation." (PMID 39156707, 2024). "The formation of vessels in the context of BXPC3 tumor masses was defined by the VWF expression pattern." (PMID 38017492, 2023). "There was a positive correlation between the tumor burden of metastatic renal cell cancer and VWF expression." (PMID 36968596, 2023). "VWF fibers promote platelet clustering and support tumor cell arrest in vessels before extravasation." (PMID 37373202, 2023). "We also screened out two potential key genes FABP4 and VWF related to tumor microenvironment using transcriptome sequencing, follow-up information and biomedical literature data, which were validated by laboratory experiments." (PMID 37950277, 2023). "ABO blood group antigens affect tumor formation, spread, and prognosis by modulating von Willebrand factor." (PMID 36788998, 2023). "Here, the presence of tumor vessels was investigated by determining the expression of VWF, a typical marker for endothelial cells." (PMID 38017492, 2023). "Podoplanin is specifically expressed in lymphatic cells, and vWF is a marker of vascular endothelial cells; these are useful markers for differentiating lymphatic and blood vessels in tumor tissues." (PMID 37175975, 2023). "The role of VEGF in neoplastic diseases also leads to enhanced TF expression and increased VWF release in ECs, thereby promoting thrombus formation and development at tumor sites." (PMID 37153586, 2023). "Administration of the anti‐vWF antibody and erdafitinib significantly delayed tumor development and resulted in smaller tumors than those in untreated mice." (PMID 37387563, 2023). "Circulating sEVs of late‐stage HCC patients markedly augment angiogenesis, tumor–endothelial adhesion, pulmonary vascular leakiness, and metastasis, which are significantly compromised by anti‐vWF antibody." (PMID 37387563, 2023). "Specifically, vWF deficiency or reduced activity can occur due to antibodies, adsorption of vWF onto tumor cells, shear stress, or increased proteolysis." (PMID 38162584, 2023). "Using immunogold labeling electron microscopy, vWF was shown to be localized on the surface of sEVs from patients at an advanced tumor stage." (PMID 37387563, 2023). "Differentially expressed genes associated with NAFLD-HCC specific tumor microenvironment were screened, of which FABP4 and VWF were featured by previous reports." (PMID 37950277, 2023). "VWF is considered to mediate tumor cell attachment to platelets and facilitate their systemic dissemination." (PMID 36991043, 2023). "Comparison of VWF levels in BC patients and healthy controls revealed higher blood VWF concentrations in BC patients, which was also correlated with tumor grade." (PMID 37569686, 2023). "The anti‐vWF antibody also significantly reduced the tumor–endothelial attachment between HUVECs and PLC/PRF/5 cells." (PMID 37387563, 2023).